MIR1253 (microRNA 1253)
Synonyms: hsa-mir-1253; MIRN1253
Gene: MicroRNA gene on chromosome 17 (2,748,078 to 2,748,182, reverse strand). Ensembl gene ENSG00000221200.
Gene Ontology:
Biological process: miRNA-mediated post-transcriptional gene silencing
Cellular component: RISC complex
Homologues: Orthologues: chimpanzee ptr-mir-1253 (100% identical). Paralogues in human: hsa-mir-1253 (66% identical).